RPP25 (ribonuclease P/MRP subunit p25)
Description:
Component of ribonuclease P, a ribonucleoprotein complex that generates mature tRNA molecules by cleaving their 5'-ends. Also a component of the MRP ribonuclease complex, which cleaves pre-rRNA sequences.
Synonyms: FLJ20374
Tractability: PROTAC: its protein half-life has been measured.
Gene: Protein-coding gene on chromosome 15 (74,954,418 to 74,956,772, reverse strand). Ensembl gene ENSG00000178718.
Subcellular location: Nucleus, nucleolus
Subcellular location (Human Protein Atlas): Nucleoplasm; Centriolar satellite
Pathways (Reactome):
Metabolism of RNA: Major pathway of rRNA processing in the nucleolus and cytosol; tRNA processing in the nucleus
Gene Ontology:
Molecular function: protein binding; ribonuclease P activity; ribonuclease P RNA binding; RNA binding; nucleic acid binding
Biological process: tRNA 5'-leader removal; RNA processing
Cellular component: multimeric ribonuclease P complex; nucleolar ribonuclease P complex; nucleoplasm; ribonuclease MRP complex; nucleus; nucleolus
Genetic constraint (gnomAD): Loss-of-function variants: 7 observed, 7.19 expected, observed/expected ratio (o/e) 0.97, 90% interval 0.55 to 1.72. That is too few expected variants to judge how well the gene tolerates losing a copy. Missense variants: 319 observed, 257.38 expected, observed/expected ratio (o/e) 1.24, 90% interval 1.13 to 1.36. Synonymous variants: 144 observed, 116.32 expected, observed/expected ratio (o/e) 1.24, 90% interval 1.08 to 1.42.
Homologues: Orthologues: chimpanzee RPP25 (98% identical), rabbit RPP25 (91% identical), pig RPP25 (90% identical), rat Rpp25 (88% identical), mouse Rpp25 (88% identical), dog RPP25 (87% identical), tropical clawed frog rpp25 (39% identical), zebrafish rpp25b (38% identical), zebrafish rpp25a (35% identical), Drosophila melanogaster Rpp25 (29% identical), Caenorhabditis elegans ZK632.14 (21% identical). Paralogues in human: RPP25L (34% identical).
Diseases named in the same sentence as RPP25 in open-access papers:
RPP25 is named in the same sentence as 14 diseases in open-access papers, as found by Europe PMC text mining. Sharing a sentence is not in itself a finding about the gene and the disease. The quoted sentences say what the papers report.
cervical cancer (4 papers, 2021 to 2024). A primary or metastatic malignant neoplasm involving the cervix. "In cervical cancer, RPP25 was negatively regulated by miR-3127-5p and miR-338-3p, while up-regulation of RPP25 promoted cell migration, invasion, and EMT." (PMID 38862431, 2024). "As a component of RNase P or MRP, RPP25 has been reported to promote the proliferation, migration, invasion, and cell cycle programs of cervical cancer cells." (PMID 36091104, 2022). "Consistent with the results of this study, previous studies have shown that RPP25 was significantly upregulated in tissues and cell lines of cervical cancer relative to the normal tissues." (PMID 34531901, 2021). "RPP25 can serve as a target gene of miR-3127-5p to promote the EMT process in cervical cancer." (PMID 34531901, 2021). "As other components of RNase P or MRP, both RPP25 and RPP30 were reported as reliable prognostic risk factors for glioblastoma multiforme and also have been reported to promote the proliferation, migration, invasion, and cell cycle program of cervical cancer cells." (PMID 36091104, 2022). "RPP25, BARD1, BRCA1, CD3EAP, CSTF2, DARS2 and DNMT3B was up-regulated in most of cervical cancer tissues compared with corresponding normal cervix tissues." (PMID 34863153, 2021).
systemic sclerosis (4 papers, 2013 to 2022). A chronic disorder, possibly autoimmune, marked by excessive production of collagen which results in hardening and thickening of body tissues. "Disorders associated with RPP25 include chromosome 15Q24 deletion syndrome and diffuse scleroderma, while systemic sclerosis can be complicated by malignancy." (PMID 35096558, 2021). "Interestingly, hRpp38 has been identified as the main component, along with Pop1, Rpp25 and Rpp30, of the Th/To autoantigen present in the sera of patients suffering from systemic sclerosis scleroderma (SSc)." (PMID 34638646, 2021).
autism (2 papers, 2023 to 2024). Persistent deficits in social interaction and communication and interaction as well as a markedly restricted repertoire of activity and interest as well as repetitive patterns of behavior. "In addition, in the prefrontal cortex (PFC) of autism patients, higher levels of H3K4me3 in the RPP25 gene resulted in decreased RPP25 transcripts." (PMID 38862431, 2024). "One report suggests that in the PFC of autism patients, transcription of RPP25 is low." (PMID 36830826, 2023).
Glioblastoma Multiforme (2 papers, 2021 to 2022). "Furthermore, both RPP25 and RPP30, another component of RNase P and MRP, were reported as reliable prognostic risk factors for glioblastoma multiforme." (PMID 36091104, 2022). "In addition, the expression of RPP25 was strongly correlated with immune cell infiltration levels in glioblastoma multiforme." (PMID 36091104, 2022). "However, the functional role of RPP25 expression in glioblastoma multiforme (GBM) is unclear." (PMID 35096558, 2021).
scleroderma (2 papers, 2013 to 2024). Scleroderma is a rare autoimmune connective tissue disorder characterized by abnormal hardening of the skin and, sometimes, other organs. "RPP25 is a prognostic predictor of high-grade glioblastoma, the development of which is elevated among patients with scleroderma (HR 6.56 95% CI 1.64–26.21)." (PMID 38892733, 2024).
Alzheimer disease (1 paper, 2021). A progressive, neurodegenerative disease characterized by loss of function and death of nerve cells in several areas of the brain leading to loss of cognitive function such as memory and language. "Among them, high RPP25 expression was enriched in pyrimidine metabolism, cell cycle, and Alzheimer’s disease–related pathways." (PMID 35096558, 2021).
osteoarthritis (1 paper, 2022). A noninflammatory degenerative joint disease occurring chiefly in older persons, characterized by degeneration of the articular cartilage, hypertrophy of bone at the margins and changes in the synovial membrane. "We found evidence (MR p < 0.05) for a causal effect of methylation on gene expression levels for two genes (ALDH1A2 and RPP25) in low-grade osteoarthritis cartilage and one gene (LTBP1) in high-grade osteoarthritis cartilage." (PMID 35679866, 2022). "For seven genes (ALDH1A2, CHMP1A, CRADD, FAM53A, LTBP1, RPP25, and TGFA), we found evidence that GWAS signals for osteoarthritis colocalize with mQTLs in these genes and are additionally associated with gene expression levels in the same tissue." (PMID 35679866, 2022). "We found such an eQTL effect below nominal significance levels for five genes in low-grade osteoarthritis cartilage (ALDH1A2, CHMP1A, FAM53A, RPP25, and TGFA), two genes in high-grade osteoarthritis cartilage (FAM53A and LTBP1), and one gene in synovium (CRADD)." (PMID 35679866, 2022).
cancer (3 papers, 2021 to 2024). A tumor composed of atypical neoplastic, often pleomorphic cells that invade other tissues. "For example, we observed loops linking enhancers to the increased expression of CD24 for V137D, and to decreased expression of RPP25 for cancer variant R118G, relative to both WT and LoF controls." (PMID 38968069, 2024). "The results showed that high RPP25 expression in GBM, LAML, LUAD, SKCM, and UVM was significantly associated with poor patient prognosis, suggesting that RPP25 may be a potential pan-cancer prognostic indicator molecule." (PMID 35096558, 2021). "A rank sum test statistical analysis was performed using R software v4.0.3, and the results showed that RPP25 was lowly expressed in GBM cancer tissues compared to normal tissues." (PMID 35096558, 2021). "In this study, we first analysed the expression and survival prognosis of RPP25 in multiple cancers by pan-cancer analysis, and then in GBM alone, and found that RPP25 was a prognostic predictor of GBM." (PMID 35096558, 2021). "The appearance of this differential may indicate that RPP25 may act at different times of tumor progression and may be a cancer suppressor in the early stage and a cancer promoter in the late stage." (PMID 35096558, 2021). "In some references found that overexpression of RPP25 could block cells in the G0/G1 phase to suppress cancer cell proliferation." (PMID 35096558, 2021).
tumor (1 paper, 2021). "The gene set enrichment analysis (GSEA) results showed that RPP25 was mainly associated with signalling pathways related to tumor progression and tumor metabolism." (PMID 35096558, 2021). "Gene pooling enrichment analysis revealed that RPP25 is involved in regulating tumor metabolism and tumor immune-related signalling pathways." (PMID 35096558, 2021). "Whether RPP25 has some predictive value in tumor progression and prognosis, what is the mechanism of this, and whether RPP25 can be a prognostic predictor or therapeutic target for GBM are a series of studies that have not been reported." (PMID 35096558, 2021). "The significance of our work is to prospectively reveal which relevant signalling pathways may be associated with the mechanism of action of RPP25 in GBM, providing a bioinformatic basis for further understanding the role of RPP25 in tumor metabolism." (PMID 35096558, 2021). "The work is also significant in that it prospectively reveals which signalling pathways may be associated with RPP25 expression in GBM and provides a bioinformatics basis for further understanding of the role of RPP25 in tumor metabolism." (PMID 35096558, 2021). "This suggests that high RPP25 expression is involved in the positive regulation of these signalling pathways and may play a role in promoting aerobic glycolysis and affecting tumor cell metabolism by driving the upregulation of these metabolic and signalling pathways." (PMID 35096558, 2021). "We retrieved the expression data of RPP25 in 21 tumor tissue cell lines from the CCLE database and analysed the expression levels of RPP25 in the 21 tissue cell lines according to their tissue sources." (PMID 35096558, 2021).
RPP25 also shares sentences with these, for which no sentence is quoted: autoimmune myocarditis (1 paper); breast carcinoma (1); diffuse scleroderma (1); pulmonary arterial hypertension (1); tuberous sclerosis (1).